CDH2 (cadherin 2)
Diseases named in the same sentence as CDH2 in open-access papers (continued):
Sharing a sentence is not in itself a finding about the gene and the disease.
melanoma (231 papers, 2005 to 2026). A malignant, usually aggressive tumor composed of atypical, neoplastic melanocytes. "The activity of genes encoding E- and N-cadherins (CDH1, CDH2) was detected in melanoma cells prepared from the spheroids." (PMID 33182777, 2020). "Expression of NFATc2, MITF, AXL, ZEB1, SNAI1 (encoding SNAIL), and CDH2 (N-Cadherin) was then evaluated at the mRNA level, by qPCR, in a larger panel of 30 melanoma cell lines." (PMID 30710146, 2019). "We investigated the distinctive phenotype of these MITF−/low melanoma cells unveiling the loss of E-cadherin (CDH1) accompanied by concomitant increased expression of N-cadherin (CDH2), a feature associated with epithelial-to-mesenchymal transition (EMT) in various cancers including melanoma." (PMID 38191367, 2024). "Following co-culture with hEo33, A375P cells exhibited increased levels of CDH1 while down-regulated CDH2, with respect to melanoma cells co-cultured with hEo5 or control." (PMID 39061080, 2024). "In fact, A375P melanoma cells up-regulated the expression of CDH1 while down-modulated CDH2 after exposure to hEo33-EV or co-culture with hEo33." (PMID 39061080, 2024). "It should be noted that CDH-2 is considered a tumor inducer in melanoma, hinting towards a more aggressive phenotype of the cells." (PMID 38791932, 2024). "Conversely, CYLD expression has been suggested to be downregulated because of elevated SNAIL1 expression, resulting in increased levels of CCND1(Cyclin-D1) and CDH2 (N-Cadherin) and enhanced proliferation, migration, and invasion of human melanomas." (PMID 35884430, 2022). "Melanoma cells were transfected with the small interfering RNA (siRNA) that targets human N–cadherin gene (CDH2)." (PMID 29492694, 2018). "Of note, based on the microscopic analysis of mouse skin xenografts of SN-MM cells, we could identify a proliferation of MITFlow/CDH1−/CDH2+/ZEB1+/CD271+ melanoma cell clusters losing most melanocytic markers, thus suggesting a MIC identity, as proposed in CM." (PMID 38191367, 2024). "Our current study has hinted that EBI3 silencing could suppress the proliferation, migration and invasion of melanoma cells, concurrent with the diminished expression of CDH2 and BCL2 yet the upregulated expression of CDH1 and BAX." (PMID 39726752, 2024). "Moreover, A375P melanoma cells significantly increased the expression of CDH1 with concomitant down-modulation of CDH2 in the presence of hEo33-EV, with respect to cells exposed to hEo5-EV or left untreated." (PMID 39061080, 2024). "However, CDH-2 expression is induced after garcinol treatment and simultaneous CDH13 knockdown, hinting towards an ongoing cancerous cellular phenotype, as CDH-2 is a marker for melanoma progression." (PMID 38791932, 2024). "CDH1 (E-cadherin) and CDH2 (N-cadherin) were also dominant in the melanoma cell pool." (PMID 33182777, 2020). "Moreover, it was demonstrated that the N-cadherin knockdown (CDH2) led to the inhibition of invasion of human melanoma cells." (PMID 33076339, 2020). "We also investigated the correlation of the seven prognostic-associated TBCs between MMP-related genes (MMP2, MMP9, MMP7, MMP14, BSG, EGFR, MMP1, MMP3) and EMT-associated genes (TWIST1, VIM, CDH2, ACTA2, ZEB1), which also indicated a central role of TBCs in melanoma." (PMID 33194704, 2020). "The gain of invasive capability was also associated with an increased expression of EMT genes (e.g., CDH2, FN1, VIM, SNAI1), as revealed by both RT-qPCR and WB analyses of bulk tumors, Bdmc+/+ and Bdmc−/− cells and siAMBRA1 human melanoma SK-Mel-5, MeWo and SK-Mel-2 cells." (PMID 33953176, 2021). "The Q1 cohort demonstrated significantly elevated expression of CCNA2, CCNB1, CCND1, and CDH2, indicating CDC25A’s potential regulatory role in coordinating melanoma cell cycle progression with EMT dynamics." (PMID 40216745, 2025).
melanoma (continued). "If melanoma cell lines express little CDH13, garcinol treatment can lead to an increase in the expression of CDH2, indicating a pro-tumorigenic phenotype of the cells." (PMID 38791932, 2024). "In melanoma cell lines expressing a small amount of CDH13, garcinol treatment can lead to an increase in the expression of CDH-2, indicating a pro-tumorigenic phenotype of the cells." (PMID 38791932, 2024). "Of relevance, the microscopic analysis of the corresponding xenotransplants allowed the identification of clusters of MITF-/CDH1-/CDH2 + /ZEB1 + /CD271 + cells, supporting the existence of melanoma-initiating cells also in MM, as confirmed in clinical samples." (PMID 38191367, 2024). "As overexpression of MITF is shown to increase E-cadherin expression, while directly repressing CDH2 (N-cadherin), MITF downregulation results in cadherin switching in melanoma." (PMID 37181747, 2023). "We found that YY1-knockdown melanoma cells were more sensitive to TGF-β1 stimulation, in that YY1 knockdown cells treated with TGF-β1, boosted the expression of the EMT genes FN1, CDH2, ZEB1, SNAI1 and VIM, among others." (PMID 35693944, 2022). "SIRT1 induces epithelial-mesenchymal transition (EMT) in melanoma cells by down-regulating E-cadherin (CDH1) and up-regulating N-cadherin (CDH2) and vimentin (VIM)." (PMID 36139919, 2022). "Also, AMBRA1 expression negatively correlated with the expression of the mesenchymal genes CDH2, FN1 and VIM, whereas a positive correlation was evident for the epithelial marker CDH1, hence suggesting that an active EMT-like process is associated with low AMBRA1 expression in human melanoma cells." (PMID 33953176, 2021). "All others demonstrate an increased expression in melanoma development, some even strongly like PMP2 (5.7-fold), TNC (10.2-fold), MMP1 (65.6-fold), and CDH2 (10.2-fold)." (PMID 34439267, 2021). "A shift to N (neuronal)-cadherin expression (cadherin 2; CDH2) allows the melanoma cells to preferentially bind to fibroblast cells that also express this CAM, and thus promotes invasion into the dermis below." (PMID 34439879, 2021). "NFATc2 showed a positive correlation with AXL, SNAI1, CDH2, and ZEB1 even in the TCGA melanoma dataset." (PMID 30710146, 2019). "RT-PCR documented mRNA expression in all the melanoma cell lines analyzed (WM115, WM266.4, and the positive controls M10 and M14) for VEGF, FGF2, CDH2, CDH5, MMP-2, MMP-9, and the two isoforms of MCAM/MUC18." (PMID 28107182, 2017). "Additionally, transition of normal melanocytic cells to malignant melanoma has a characteristic of EMT, which includes the disrupted adherens junctions resulted from the down-regulation of CDH1 and the up-regulation of CDH2." (PMID 39726752, 2024). "There are several subtypes of cadherins, however type I cadherins are the most relevant to melanoma, and include: epithelial cadherin (E-cadherin, CDH1), present in epithelial cells, melanocytes and keratinocytes; neural cadherin (N-cadherin, CDH2); and placental cadherin (P-cadherin, CDH3)." (PMID 37181747, 2023). "Indeed, we observed changes in important EMT markers and regulators such as ZEB1, CDH1 (E-Cadherin), CDH2 (N-Cadherin), SNAI2, and TGFß1 in the MITF-KO cells as well as in TCGA melanoma samples." (PMID 33438577, 2021). "Here we show that SALL4 can build a protein complex together with HDAC2 also in human melanoma cells and that SALL4 and HDAC2 together directly bind to genes involved in melanocyte and melanoma biology, such as VEGFR-1, CDH2 (N-cadherin), FN1, TGFBR2, MITF, and others." (PMID 34417458, 2021). "In the TCGA melanoma dataset, the top 312 genes with a positive correlation (down to Spearman r = 0.5) with the prototypic EMT marker ZEB1, were also positively correlated with SNAI1, NFATc2, CDH2, and AXL, but negatively with MITF and CDH1." (PMID 30710146, 2019).
melanoma (continued). "QRT-PCR experiments showed that naïve 501mel melanoma cells exposed to the secretome of melanoma cells rendered senescent by MITF silencing exhibited an increased level of SNAIL1, TWIST1, Fibronectin1, N-Cadherin (CDH2) mRNAs whereas MITF and E-Cadherin (CDH1) transcripts were markedly decreased." (PMID 24344100, 2013). "EBI3 was evidently highly-expressed in melanoma, and silencing of EBI3 could visibly suppress the survival and migration/invasion of melanoma cells, concurrent with the increased levels of BAX and CDH1 and the decreased expressions of BCL2 and CDH2." (PMID 39726752, 2024).
lung carcinoma (218 papers, 2012 to 2026). "IHC is a widespread method for detecting lymph node micrometastases based on antigen-antibody responders and a low CDH1/CDH2 ratio has recently been shown to be associated with lung cancer micrometastases." (PMID 37509396, 2023). "Elevated expression of CDH2 implicated poor prognosis in various cancers such as lung cancer, prostate cancer,25, and glioma." (PMID 35880695, 2023). "A previous study demonstrated that EMT is involved in the process of metastatic dissemination to the brain, and the EMT driver genes that were upregulated in our study (SOX10, TWIST1, CDH2) may have potential as biomarkers in risk stratification for BM in suspected early-stage lung cancer." (PMID 37139160, 2023). "For example, SMAD2 activated by TGF-β signaling upregulates the expression of EPHB1, which further promotes epithelial–mesenchymal transition (EMT) by elevating CDH2 expression in lung cancer." (PMID 40548257, 2025). "We have shown in this study that knockout of GluIIβ from lung cancer cell line significantly decreased the expression of CDH2 as well as the reduction of many other cell surface proteins including CDH4, PD-L1 (B7-H1) and PD-L2 (B7-DC)." (PMID 38245670, 2024). "For several cancer cells, including lung cancer, the role of CDH2 in cell migration and invasion has been reported." (PMID 35058980, 2022). "Consistent with this, suppression of ID1 increased promoter occupancy of TCF4 and TWIST1 on E-box containing CDH1 and CDH2 promoter loci, and increased TCF4 and TWIST1 were observed on CDH1 and CDH2 promoters in FOXA1 knockdown A549 lung cancer cells." (PMID 35897813, 2022). "By analyzing the differentially expressed genes in animal models and human tissue cohorts, several genes, including CDH2, KIFC1, and FALZ, were identified to be highly associated with lung cancer brain metastasis." (PMID 26883469, 2016). "Because microRNAs regulate many biological functions and disease processes (e.g., cancer) by down-regulating their target genes, microRNA microarrays were used to identify ADAM9-regulated miRNAs that target CDH2 in aggressive lung cancer cells." (PMID 24705471, 2014). "Currently, several genes related to lung cancer brain metastases have been identified, such as CDH2 and ADAM9." (PMID 24705471, 2014). "Similarly, primary EGFR‐mutated lung cancer cells (MGH119) showed higher CEACAM5 and epithelial marker CLDN1 expression but lower mesenchymal marker CDH2 expression than their EGFR‐TKI gefitinib‐resistant counterparts (MGH119GR)." (PMID 40856433, 2025). "Furthermore, PIK3C2G, FIBIN, CHRNA1, NPNT, MEOX1, and POU2F2 linked obesity and lung cancer, while PTPRQ, SSUH2, CILP2, CDH2, ABCA12, CPXM1, and L1CAM linked hypertension and lung cancer." (PMID 36685671, 2023). "Similarly, decreased CDH1 and increased CDH2 were observed in FOXA1-silenced H358 lung cancer cells." (PMID 35897813, 2022). "To further validate these novel players in lung cancer cell migration, we selected five candidates—DSE, CPA4, FLNC, TUBB6, and BICC1—and the positive control CDH2, which were upregulated in fast cells and also associated with poor overall survival in NSCLC patients." (PMID 33934493, 2021). "miR-124 can inhibit the expression of CDH2, which might lead to a therapeutic strategy targeting CDH2 in human lung cancer." (PMID 33329729, 2020). "In our study, we observed upregulation of E-cadherin and CDH2 in both lung cancers." (PMID 31921388, 2019). "It has been shown that the expression of CDH2 may potentially cause mesenchymal phenotype by EMT and the promotion of the survival of lung cancer cells with drug-resistant, suggesting that CDH2 is a potential therapy target for anti-cancer cells." (PMID 31217907, 2019).
lung carcinoma (continued). "To investigate which miRNAs could regulate CDH2 expression in brain metastatic lung cancer cells, we examined the miRNA expression profiles in these cells and their parental cells using an Illumina miRNA microarray." (PMID 24705471, 2014). "To examine ERBIN's effect on TGF‐β‐induced EMT, we analyzed breast and lung cancer patient cohorts and found that ERBIN positively correlates with the epithelial marker CDH1 (encoding E‐Cadherin) and negatively correlates with the mesenchymal markers CDH2 (encoding N‐Cadherin) and SNAI1." (PMID 40859866, 2025). "Next, the GSEA analysis was conducted using a gene set comprising CDH1, CDH2, and CDH3 to investigate their collective role in lung cancer." (PMID 40860670, 2025). "Here, we found that FOXA1 knockdown decreased CDH1 (epithelial marker) but increased CDH2, VIM, SNAI2, and PTHLH (mesenchymal markers) in A549 lung cancer cells." (PMID 35897813, 2022). "Hsa_circ_0006692 modulated EMT of lung cancer cells via the stimulation of CDH1, CDH2, VIMENTIN, and MMP7." (PMID 35627232, 2022). "Previous studies have demonstrated that TCF4 can interact with TWIST1 to promote the expression of EMT-related genes, such as CDH2, VIM, SNAI1, and SNAI2, in embryonic stem and lung cancer cells." (PMID 35406121, 2022). "As an epithelial marker, CDH1, was decreased and mesenchymal markers, CDH2, VIM, SNAI2, and ITGA5 were increased in PGC1α-silenced epithelial types of A549, H358, and Calu-1 lung cancer cells." (PMID 33917757, 2021). "In the lung cancer, the driver triad hsa_circ_0051620| SLC1A5–hsa-miR-338-3p—CDH2 and hsa_circ_0066954| POLQ–hsa-miR-338-3p—CDH2 shows the downregulation of the driver gene CDH2, which increases the survival of the patients." (PMID 34055888, 2021). "Pearson correlation analysis showed that LINC01010 was negatively correlated with EMT markers (CDH2 and CTNNB1) in lung cancer patient samples." (PMID 32518519, 2020). "Some research results indicate that overexpression of CDH2 can increase the invasive ability and induce EMT in lung cancer cells." (PMID 32766727, 2020). "In the current study, we aimed to better understand the relationship between CDH2 and ADAM9 in lung cancer brain metastasis." (PMID 24705471, 2014). "The expression levels of three genes, CDH2 (N-cadherin), KIFC1, and FALZ, was found in one study to be highly predictive of BM in early and advanced lung cancer." (PMID 23284751, 2012). "Moreover, SMAD3 knockdown suppresses the migration and invasion of lung cancer cell line, and the expression of VIM and CDH2 was decreased by SMAD3 knockdown." (PMID 37121971, 2023). "In addition, ectopic FOXA1 expression significantly reversed TGFβ1-mediated expression of EMT markers, such as CDH1, CDH2, VIM, SNAI2, and PTHLH, in A549 lung cancer cells." (PMID 35897813, 2022). "Additionally, in NSCLC, overexpression of CDH2 (N-cadherin), KIFC1, and FALZ is highly predictive of metastasis to the brain in early and advanced lung cancer." (PMID 22481931, 2012). "To examine whether the induction of EMT reduces HER2 expression, we analyzed mRNA expression of ERBB2, epithelial phenotype markers CDH1, EPCAM, MUC1 and OCLN, mesenchymal phenotype markers CDH2, FN1, SNAI2, and VIM in the A549 cell line (HER2-high human lung cancer epithelial cell line)." (PMID 34575017, 2021). "Similarly, in lung cancer, the circRNAs, namely, hsa_circ_0051620| SLC1A5 and hsa_circ_0066954| POLQ, are upregulated and are shown to interact with and regulate driver genes, namely, ADAM17, CDH2, RUNX2, and ZBTB18, through miR-338-3p." (PMID 34055888, 2021). "Our previous study demonstrated that ADAM9 promotes lung cancer metastasis by enhancing the function of CDCP1 and regulates the expression of several genes through dysregulation of miRNAs, such as activation of N-cadherin (CDH2; cadherin 2) and CDCP1 through miR-218." (PMID 28537886, 2017).